ARRB2 (arrestin beta 2)
Diseases named in the same sentence as ARRB2 in open-access papers (continued):
Sharing a sentence is not in itself a finding about the gene and the disease.
Sepsis (4 papers, 2017 to 2025). Sepsis is defined as life-threatening organ dysfunction caused by a dysregulated host response to infection. "increased miR-155 expression through systemic administration of miR-155 mimic attenuates cardiac dysfunction and improves late sepsis survival by targeting JNK associated inflammatory signaling and ARRB2 mediated immunosuppression." (PMID 40041174, 2025). "To further elucidate the relationship between miR-155 and Arrb2, and their effect on late-septic mice survival, we tested miR-155 expression in Arrb2 TG mice myocardium, meanwhile observed Arrb2 TG mice survival in late sepsis model." (PMID 28525390, 2017). "We conclude that increased miR-155 expression through systemic administration of miR-155 mimic attenuates cardiac dysfunction and improves late sepsis survival by targeting JNK associated inflammatory signaling and Arrb2 mediated immunosuppression." (PMID 28525390, 2017). "In our study, Arrb2 TG mice were observed to be more susceptive to late sepsis than WT mice, as death occurred with the highest frequency on day 6–10 after sepsis, which was earlier than in WT mice (day 10–12)." (PMID 28525390, 2017). "We found that sepsis Arrb2 TG mice were immunosuppressive, characterized by reduced pro-inflammatory (TNF-α, INF-γ) and increased anti-inflammatory (IL-10, IL-4) cytokines expression." (PMID 28525390, 2017). "After CLP in Arrb2 TG mice, transfection of miR-155 mimic suppressed myocardial Arrb2 expression by 55.6% compared with untreated Arrb2 TG mice in late sepsis." (PMID 28525390, 2017). "Additionally, miR-155 can target JNK-related inflammatory signals and β-arrestin 2 (ARRB2)-mediated immunosuppression to attenuate cardiac insufficiency and improve survival in late-stage sepsis patients." (PMID 40041174, 2025). "Similarly, ARRB2 was found to negatively regulate inflammation response in the setting of polymicrobial infections and sepsis." (PMID 29636059, 2018). "Overexpression of Arrb2 exacerbates the mortality and immunosuppression in late sepsis mice." (PMID 28525390, 2017). "CLP increased Arrb2 expression (2-fold) compared to sham control on day 10 after sepsis." (PMID 28525390, 2017). "We also evaluate the effect of miR-155 on cardiac function in Arrb2 TG mice at day 10 after sepsis." (PMID 28525390, 2017). "We also found that Arrb2 exacerbated the mice mortality and immunosuppression in late sepsis." (PMID 28525390, 2017). "Moreover, overexpression of β-arrestin 2 (Arrb2) exacerbated the mice mortality and immunosuppression in late sepsis." (PMID 28525390, 2017). "miR-155/Arrb2 may be an effective target in the management of sepsis and in the field of infectious disease, and our mice model also provides an important insight into particular mechanisms of sepsis that may have a comparable role in humans." (PMID 28525390, 2017). "However, the effect of Arrb2 on cardiac function during late sepsis remains unknown." (PMID 28525390, 2017). "Transfection of miR-Con did not alter the expression of Arrb2 in the presence and absence of sepsis." (PMID 28525390, 2017). "Transfection of miR-155 mimic increased miR-155 expression in the presence and absence of sepsis, when compared with untreated Arrb2 TG mice." (PMID 28525390, 2017).
colorectal cancer (3 papers, 2022 to 2024). A primary or metastatic malignant neoplasm that affects the colon or rectum. "In colorectal cancer, increased expression of arrestin beta 2 (ARRB2) could upregulate WTAP expression; however, the specific regulation mechanism is unclear." (PMID 36139062, 2022).
frontotemporal dementia (3 papers, 2025). Frontotemporal dementia (FTD) comprises a group of neurodegenerative disorders, characterized by progressive changes in behavior, executive dysfunction and language impairment, as a result of degeneration of the medial prefrontal and frontoinsular cortices. "Similarly, ARRB2 (Beta-Arrestin 2) is involved in neurodegeneration by interacting with pathways linked to protein accumulation, such as amyloid-beta in Alzheimer’s and tau in frontotemporal dementia." (PMID 40643497, 2025). "Arrb2 is closely associated with the development of several neurodegenerative diseases, such as Parkinson’s disease (PD), frontotemporal dementia (FTD), and Alzheimer’s disease (AD)." (PMID 40428426, 2025).
Parkinson disease (3 papers, 2020 to 2025). A progressive degenerative disorder of the central nervous system characterized by loss of dopamine producing neurons in the substantia nigra and the presence of Lewy bodies in the substantia nigra and locus coeruleus. "ARRB2 also influences neuroinflammation, synaptic dysfunction, and may regulate alpha-synuclein in Parkinson’s disease, suggesting a similar role in HD." (PMID 40643497, 2025).
schizophrenia (3 papers, 2014 to 2022). A major psychotic disorder characterized by abnormalities in the perception or expression of reality. "Clinical data indicate that ARRB2 is associated with Chinese schizophrenia patients." (PMID 35062349, 2022). "The genetic interaction for mitochondria function and schizophrenia were illustrated by DRD2 linked to NDUFS7 through protein-protein interactions of FLNA and ARRB2." (PMID 25522158, 2014). "The genetic interaction between mitochondria function and schizophrenia may be revealed by DRD2 linked to NDUFS7 through protein-protein interactions of FLNA and ARRB2." (PMID 25522158, 2014). "Consistent with the ARRB2/PP2A complex formation, the ARRB2/PP2A/AKT1/GSK3 signal pathway facilitates the dephosphorylation and deactivation of AKT, resulting in the activation of GSK3, and may be an attractive potential factor in the DA hypothesis of schizophrenia." (PMID 35062349, 2022).
virus infection (3 papers, 2016 to 2020). "Microinjections of Arrb2-lentiviral (Arrb2-LV) vector into one side of SDH resulted in unilateral virus infection revealed by GFP-labelling, followed by increase in Arrb2 mRNA levels in SDH." (PMID 27538456, 2016). "Furthermore, the production of Ifnb, Isg15, and Ccl5 was increased in Arrb2−/− mouse embryonic fibroblasts (MEFs) transfected with K171R mutant compared with WT β-arrestin 2, whereas K171Q mutant abolished the positive regulation during virus infection." (PMID 33243993, 2020).
autism spectrum disorder (2 papers, 2023 to 2025). A spectrum of developmental disorders that includes autism, and Asperger syndrome. "Further, mutations in some of the genes have been associated with neurological phenotypes, such as Aicardi-Goutierès syndrome (RNASEH2C), intellectual disabilities and epilepsy (DNM1), and autism spectrum disorder (ARRB2)." (PMID 37147306, 2023).
bladder cancer (2 papers, 2020 to 2023). "WDR4 knockdown inhibited the metastasis and proliferation of cancer cells compared with that of the control cells, and simultaneous silencing of ARRB2 significantly restored the metastasis and proliferation of bladder cancer cells." (PMID 37783676, 2023). "As an adaptor, WDR4 binds DDX20 and represses the transcription factor Egr1, thereby inhibiting the transcriptional expression of ARRB2 and ultimately promoting the progression of bladder cancer." (PMID 37783676, 2023). "Our study demonstrated that ARRB2 inhibited the metastasis and proliferation of bladder cancer cells." (PMID 37783676, 2023). "One study found that ARRB2 is a potential prognostic indicator for progression and the chemotherapy response in bladder cancer, and overexpression of ARRB2 leads to reduced tumor growth and an enhanced response to chemotherapy." (PMID 37783676, 2023). "Consistently with these observations, overexpression of ARRB2 reduced spheroid formation and viability confirming its role in regulating self-renewal in bladder cancer." (PMID 33297302, 2020). "Studies on bladder cancer cell lines suggest that ARRB2 negatively regulates the cancer stem cell (CSC) marker Aldehyde dehydrogenase (ALDH), which is implicated in the maintenance of CSC stemness and is important for the progression of bladder cancer." (PMID 33297302, 2020). "ARRB2 functions as a negative regulator of stem cell properties in bladder cancer, however, it induces self-renewal in leukemia where it plays a crucial role in stem cell maintenance." (PMID 33297302, 2020). "ARRB1 and ARRB2 appear to have opposing functions in regulating stem cell properties in bladder cancer." (PMID 33297302, 2020). "In addition, ARRB2 has been reported to inhibit the growth and progression of bladder cancer and increase the response to chemotherapy." (PMID 37783676, 2023). "ARRB2 also seems to regulate the transcription factor STAT3 in bladder cancer." (PMID 33297302, 2020). "Subsequently, we examined whether ARRB2 could reverse the effects of WDR4 in bladder cancer cells." (PMID 37783676, 2023). "ARRB2 may act as a tumor suppressor regulated by the WDR4-DDX20 complex in bladder cancer." (PMID 37783676, 2023). "Moreover, ARRB2 was shown to regulate resistance of bladder cancer cells towards Gemcitabine." (PMID 33297302, 2020). "The results of mechanistic studies suggested that WDR4 can recruit DEAD-box helicase 20 (DDX20) into the nucleus and inhibit the transcriptional expression of arrestin beta 2 (ARRB2), thus promoting LN metastasis and progression of bladder cancer." (PMID 37783676, 2023). "Strikingly, ARRB2 was found to negatively regulate both KRT14 and KRT17 in bladder cancer cell lines." (PMID 33297302, 2020). "ARRB2 depletion in bladder cancer cells was shown to induce phosphorylation/activation of STAT3, whereas overexpression of ARRB2 had the opposite effect." (PMID 33297302, 2020).
breast carcinoma (2 papers, 2012 to 2022). "Defective SUMOylation of ARRB2 inhibits the migration of breast cancer cells and has been shown to be involved in ARRB2-dependent metabolic regulation of breast cancer cells." (PMID 36284630, 2022). "For example, Oncomine analysis of breast cancer data showed that ARRDC2/3/4 and TXNIP appear among the genes most downregulated between normal and cancer tissue, whereas ARRB2 appears among the genes most upregulated." (PMID 23236378, 2012).
glioma (2 papers, 2020 to 2022). A benign or malignant brain and spinal cord tumor that arises from glial cells (astrocytes, oligodendrocytes, ependymal cells). "ARRB2 plays a negative regulatory role in glioma growth, invasion, and metastasis by reducing HIF-1α expression and inhibiting angiogenesis." (PMID 36284630, 2022).
hepatocellular carcinoma (2 papers, 2022 to 2023). A malignant tumor that arises from hepatocytes. "β-arrestin 2 (ARRB2) can inhibit hepatocellular carcinoma (HCC) cell migration and invasion through Akt pathway down-regulation." (PMID 37443143, 2023).
ischemia (2 papers, 2020). A hypoperfusion of the BLOOD through an organ or tissue caused by a PATHOLOGIC CONSTRICTION or obstruction of its BLOOD VESSELS, or an absence of BLOOD CIRCULATION. "Second, endothelial cells were also associated with ischemia-induced neovascularization, and this study showed that Arrb2 could improve endothelial cells migration, consistent with previous findings." (PMID 32863967, 2020). "In the hepatic ischemia-reperfusion injury mouse models, we observed significantly greater apoptosis in the liver tissues of ARRB2 KO mice compared with WT mice after hepatic ischemia-reperfusion, as detected by TUNEL staining and increased cleaved caspase-3 expression." (PMID 33323551, 2020). "Therefore, Arrb2 might contribute to revascularization after femoral artery ligation-induced ischemia." (PMID 32863967, 2020). "Considering that ARRB2 has been shown to inhibit the apoptosis of hepatocytes and promote their proliferation in mice suffering from hepatic ischemia reperfusion, our results suggested that ARRB2 may protects mice against hepatic IRI by activating PI3K/Akt signaling." (PMID 33323551, 2020).
lung adenocarcinoma (2 papers, 2022 to 2023). A carcinoma that arises from the lung and is characterized by the presence of malignant glandular epithelial cells. "According to the results of Cox regression analysis, we found that ARRB2 was significantly different in lung adenocarcinoma (LUAD, P = 0.0260), pancreatic cancer (PAAD, P = 0.0155), and PRAD (P = 0.0003)." (PMID 36284990, 2022).
myocardial infarction (2 papers, 2014 to 2018). Gross necrosis of the myocardium, as a result of interruption of the blood supply to the area, as in coronary thrombosis. "We transplanted CSCs from WT or Arrb2 KO mice into mice with myocardial infarction to analyse the function of Arrb2 in CSC-participating cardiac repair." (PMID 24974728, 2014). "Furthermore, we transplanted WT or Arrb2 KO Sca-1+ CSCs to Arrb2 KO mice with myocardial infarction, high level of Arrb2 equal to better performance of cardiac function, verified the vital function of Arrb2 in cardiac repair." (PMID 24974728, 2014). "Another study declared that increased ARRB2 in infiltrated macrophages after myocardial infarction (MI) plays a protective role in MI-induced inflammation." (PMID 29636059, 2018). "Arrb2 protein was expressed in Arrb2-KO mice after transfer of Sca-1+ CSCs from WT mice, which suggests that the transplanted cells could survive in the mice with myocardial infarction." (PMID 24974728, 2014). "To determine the role of the Arrb2/miR-155/GSK3β pathway in CSC-mediated cardiac repair in vivo, we injected stem cells from WT and KO mice into the hearts of mice with myocardial infarction." (PMID 24974728, 2014).
neuroblastoma (2 papers, 2021 to 2023). Neuroblastoma (NB) is the most common solid, extracranial childhood tumor.
Stroke (2 papers, 2018 to 2019). Sudden impairment of blood flow to a part of the brain due to occlusion or rupture of an artery to the brain. "Taken together, our data indicated that ARRB2 deficiency aggravated stroke outcomes induced by NOD2 stimulation after cerebral I/R injury in mice by enhancing inflammation." (PMID 30793522, 2019). "Moreover, we further confirmed that ARRB2 negatively regulated NOD2‐induced inflammatory response, as ARRB2‐deficient mice exacerbated stroke outcomes and deletion of ARRB2 aggravated the NF‐κB signalling pathway induced by NOD2 stimulation after cerebral I/R injury." (PMID 30793522, 2019). "In summary, these findings suggest that stroke-induced activation of the sympathetic system significantly contributes to splenic ARRB2 expression and monocyte dysfunction." (PMID 29636059, 2018). "Splenic ARRB2 expression was significantly increased after stroke and also showed a significant positive correlation with the sympathetic system activity." (PMID 29636059, 2018). "In the present study, for the first time, we demonstrated that elevated ARRB2 expression in response to stroke-induced sympathetic hyperactivity was deeply involved in the sympathetic-triggered monocyte dysfunction." (PMID 29636059, 2018). "In this study, the obtained results indicate that splenic ARRB2 is elevated after stroke due to hyperactivation of the sympathetic system." (PMID 29636059, 2018). "Hopefully, clarifying the immunological function of ARRB2 in SIDS can contribute to the identification of novel therapeutic targets for the devastating condition of stroke." (PMID 29636059, 2018). "The present study investigated a novel function of ARRB2 that was playing a dominant role in stroke-induced immunodepression." (PMID 29636059, 2018). "ARRB2 is implicated in the sympathetic-triggered SIDS, in particular, monocyte dysfunction after stroke." (PMID 29636059, 2018). "Finally, the in vivo study clearly confirmed that ARRB2 negatively regulated NOD2‐induced inflammatory response, as ARRB2 deficiency exacerbated stroke outcomes and aggravated the NF‐κB signalling pathway induced by NOD2 stimulation after cerebral I/R injury." (PMID 30793522, 2019). "Moreover, blockade of the sympathetic system by propranolol prominently reverses a stroke-induced immunodepression symptom as well as splenic ARRB2 expression." (PMID 29636059, 2018). "Thus, subsequent in vivo and in vitro studies based on other cell populations, such as T cells and microglial cells, will be required to further confirm the role of ARRB2 in post-stroke inflammatory reactions." (PMID 29636059, 2018). "Accordingly, ARRB2 may be a promising therapeutic target for the immunological management of stroke in clinic." (PMID 29636059, 2018). "Even though the multiple functions of ARRB2 have been explored in cardiac diseases and infections, very limited information is available about alterations in the expression and functions of ARRB2 after stroke." (PMID 29636059, 2018). "Accordingly, ARRB2 may be a promising therapeutic target for the immunological management of stroke in a clinic." (PMID 29636059, 2018). "Besides, the achieved results reveal that stroke induces increased splenic ARRB2 expression that has a significant positive correlation with the sympathetic system activity." (PMID 29636059, 2018). "However, it still remains indistinct whether ARRB2 functions as a regulator in sympathetic-triggered splenic monocyte dysfunction after stroke." (PMID 29636059, 2018). "Hence, ARRB2 might be a promising therapeutic target for the management of stroke." (PMID 29636059, 2018). "Therefore, the current study firstly attempts to verify whether ARRB2 expression is increased after stroke, and further evaluates the correlation between ARRB2 expression and the sympathetic system activity through establishing models of middle cerebral artery occlusion (MCAO)." (PMID 29636059, 2018).
alcohol addiction (1 paper, 2025). "Another intriguing example is the association between β-arrestin 2 (ARRB2) protein expression and alcohol addiction." (PMID 40124499, 2025).
Anxiety (1 paper, 2025). Intense feelings of nervousness, tension, or panic often arise in response to interpersonal stresses. "Through multi-omics integration across the amygdala, cerebellum, hippocampus, and prefrontal cortex, our findings demonstrate that increased Arrb2 expression significantly correlates with core autism phenotypes, including learning stimulus extinction, social impairments, and anxiety." (PMID 40428426, 2025).
asthma (1 paper, 2022). "Increased ARRB2 expression in OVA (ovalbumin)-challenged mice and diminished inflammatory responses in ARRB2 deficiency mice implied the key role of ARRB2 in the pathogenesis of asthma." (PMID 35958620, 2022). "Consistently, our study reinforced the essential regulatory role of ARRB2, as the target of miR-365-3p, in the inflammatory response in IL-17-dependent asthma pathogenesis." (PMID 35958620, 2022). "The further mechanistic study demonstrated that miR-365-3p was a negative regulator in IL17-mediated inflammation in both murine and human airway cells via miR-365-3p/ARRB2/cytokines axis, which may provide experimental evidence for the potential therapeutic targets of asthma." (PMID 35958620, 2022). "ARRB2, well known to regulate G protein-coupled receptor function and receptor internalization, has been also recognized as an important pro-inflammatory mediator by promoting CD4+ T cells migration, Th2 cell chemotaxis, and inflammatory cytokine production in asthma." (PMID 35958620, 2022).